PRMT5 (protein arginine methyltransferase 5)
Diseases named in the same sentence as PRMT5 in open-access papers (continued):
Sharing a sentence is not in itself a finding about the gene and the disease.
cancer (continued). "Despite this, the mechanisms by which PRMT5 contribute to progression of a specific cancer type, particularly that of carcinomas, is largely unknown." (PMID 29876520, 2018). "Importantly, several small selective pharmaceutical inhibitors for PRMT5 were developed for cancer treatment." (PMID 29679004, 2018). "In light of these positive results, it is going to be important to develop an experimental therapeutic program that can facilitate translational research, which explores PRMT5 inhibition both alone and in combination with other drugs known to inhibit cancer cell growth." (PMID 30613353, 2018). "Furthermore, the role of PRMT5 in regulating expression and stability of key transcription factors that control normal stem cell function as well as cancer stem cell renewal will be discussed." (PMID 30613353, 2018). "Together, our findings highlight the importance of PRMT5 in BCSC maintenance and suggest that small-molecule inhibitors of PRMT5 or downstream targets could be an effective strategy eliminating this cancer-causing population." (PMID 29262329, 2017). "Similarly, it was previously seen in cancer cells in which treatment with a drug, AS1411 (a quadruplex-forming oligonucleotide aptamer) led to the decreased association of PRMT5 with known gene promoters (cyclin E2, tumor suppressor genes)." (PMID 28678843, 2017). "Taken together, the “MP/PRMT5/histone R3” pathway plays a critical role in tumorigenesis and cancer development, therefore the pharmacological interventions of this pathway by targeting MP may have important and promising clinical implications in therapeutics." (PMID 28074910, 2017). "In order to determine whether PRMT5 is a tumor promoter in PDAC and CRC, we first examined PRMT5 expression in both cancers by Western blotting and immunohistochemistry (IHC) assay." (PMID 28591716, 2017). "Consequently, cancers with loss of MTAP and therefore already impaired PRMT5 activity are hypersensitive toward PRMT5 inhibitors." (PMID 28725214, 2017). "Taken together, our results strongly imply that therapeutic targeting of PRMT5 could be an effective way of eradicating the cancer stem cell compartment." (PMID 29262329, 2017). "Taken together, we hypothesize that PRMT5 overexpression can promote the cancer phenotype through PRMT5-mediated NF-κB activation, whereas using PR5-LL-CM01 to block this activity could impede PDAC and CRC progression." (PMID 28591716, 2017). "Moreover, we found PRMT5 as a novel cofactor of SHARPIN in regulating cancer-related gene expression." (PMID 28903384, 2017). "It was shown that PRMT5 regulated apoptosis in some cancer cells." (PMID 27480244, 2016). "There are several strategies to inhibit PRMT5 overexpression in cancer." (PMID 26541651, 2015). "PRMT5 is present both in the cytoplasm and in the nucleus of cancer cells." (PMID 26563484, 2015). "PRMT5 is also involved in a wide variety of cellular processes, including RNA processing, transcriptional regulation, and signal transduction pathway regulation that are highly relevant to the pathogenesis of cancer." (PMID 26729154, 2015). "Inhibition of PRMT5 overexpression can induce apoptosis in different types of cancer." (PMID 26541651, 2015). "PRMT5 has pleiotropic regulatory roles in the cytoplasm and nucleus in normal cells, and has been shown to be crucial for normal development, emphasising the importance of defining PRMT5 substrates in normal and cancer cells." (PMID 25475372, 2015). "PRMT5 inhibition may therefore represent a novel alternative for treatment of NB and other cancers driven by the MYCN oncoprotein." (PMID 25475372, 2015).
cancer (continued). "PRMT5 silencing can induce apoptosis in different types of cancer." (PMID 26078354, 2015). "All 9 carcinomas had cytoplasmic and nuclear PRMT5 expression." (PMID 24326178, 2013). "In addition, we demonstrated that PRMT5 and p44 localized in the nucleus in benign prostate epithelium but localized in the cytoplasm in prostate premalignant and cancer tissues." (PMID 22952863, 2012). "PRMT5 inhibitors may suppress cancer cell growth by targeting these processes." (PMID 40264765, 2025). "Notably, PRMT5 expression is upregulated in several cancers." (PMID 40091834, 2025). "The goal was to understand whether PRMT5 regulation of gene expression extends to other cancers." (PMID 40735501, 2025). "Type II methyltransferase PRMT5 has been reported to affect cancer biological functions in multiple manners, like histone methylation, inhibition of tumor suppressors or promotion of oncogenes, thus driving cancer cell growth, metastasis, and treatment resistance." (PMID 40384988, 2025). "Additionally, it suggests that this function extends to all cancer types, and depletion or inhibition of PRMT5 could be used as a therapeutic cancer treatment target." (PMID 40735501, 2025). "Moreover, the symmetric dimethylation of c-Myc was reduced in PRMT5-silenced cancer cells." (PMID 40675966, 2025). "In addition to enhancing Prmt5 inhibition, methionine restriction could also augment cancer immunotherapy." (PMID 39862967, 2025). "Thus MTAP-deleted cancer cells are more sensitive to PRMT5 inhibitors." (PMID 38638566, 2024). "Therefore, PRMT5 has recently emerged as a promising target in many cancers." (PMID 39711357, 2024). "Importantly, no significant toxicities or cell death was observed in the normal guts mucosa of mice treated with MTDIA and AG-270 in contrast to those treated with PRMT5 inhibitor GSK3326595, highlighting an additional benefit of this treatment and the essential function of PRMT5 in cancers." (PMID 38000655, 2024). "Therefore, although the dependence may vary by cancer type, our data demonstrate that the PRMT5/MEP50/STAT3 pathway is important for CSCs in NSCLC." (PMID 38760429, 2024). "Therefore, we stained adjacent sections for E-cadherin, vimentin, Slug, laminin 5, PRMT1, and PRMT5 and investigated whether the expression levels of these molecules and/or those of MST2 and YAP1 were associated with the cancer cell invasion pattern." (PMID 38444414, 2024). "Consequently, inhibiting PRMT5 may contribute to the recovery of the immune cycle and enhance the immune system’s ability to combat cancer cells." (PMID 38827324, 2024). "Furthermore, PRMT5 expression levels have been reported to be upregulated in various cancers." (PMID 38760429, 2024). "Therefore, developing effective PRMT5 inhibitors is crucial for improving cancer treatment." (PMID 39614393, 2024). "In addition, we wished to test whether silencing the activity of PRMT5 alters the localization of FXR1 in cancer cells." (PMID 38709899, 2024). "Therefore, inhibiting PRMT5 may help recover the cancer-immunity cycles, making it a potentially promising therapeutic target." (PMID 36980950, 2023). "Thus, an increase in PRMT5 expression will positively impact cancer proliferation." (PMID 37795443, 2023). "Moreover, this is the first study to propose that PRMT5 acts as a cancer suppressor in ccRCC." (PMID 37781030, 2023). "To examine whether human lncRNA genes behave in a similar way to that observed in murine cancer cells and further investigate the effect of PRMT5 and E2F1, we explored lncRNA expression upon PRMT5 inhibition and CRISPR knock-out (KO) of the E2F1 gene in HCT116 cells derived from human CRC11." (PMID 36841868, 2023).
cancer (continued). "Therefore, modulating DNA damage response and repair proteins through PRMT5 inhibition may increase the sensitivity of cancer cells to PARP inhibition." (PMID 37596538, 2023). "Reduction or inhibition of PRMT5 could therefore be an approach for treating cancer." (PMID 37795443, 2023). "Moreover, studies have suggested that PRMT5 could be a potential target for developing anti-cancer therapies, as inhibiting its activity has been shown to inhibit the growth of cancer cells and reduce tumor size." (PMID 37400960, 2023). "Therefore, our study reveals a critical regulatory mechanism of PRMT5 in cancers." (PMID 37173967, 2023). "Notably, PRMT5 inhibitors have gained a strong interest for developing new treatments for cancer." (PMID 36830948, 2023). "Furthermore, PRMT5 has been shown to induce autophagy and inhibit apoptosis in certain cancers." (PMID 36769189, 2023). "Therefore, PRMT5 is an attractive target for anti-cancer drug development." (PMID 36980950, 2023). "Furthermore, emerging evidence shows that PRMT5 is involved in immune evasion in cancer." (PMID 36980950, 2023). "With an intimate involvement in transcriptional and post-transcriptional regulation, it is not surprising that aberrant expression of PRMT5 is associated with a variety of cancers, including small cell lung cancer, breast cancer, ovarian cancer, and acute lymphoblastic lymphoma." (PMID 35744905, 2022). "Thus, PRMT5 is an attractive cancer target for small-molecule inhibition." (PMID 35111150, 2021). "Thus, they revealed a PRMT5-regulated DI-splicing program as an exploitable cancer vulnerability." (PMID 33782401, 2021). "However, the relationship between cancer growth inhibition and the observed PRMT5 inhibitor effect on altered splicing and these three pathways remains unclear." (PMID 34680285, 2021). "However, PRMT5 inhibitors represent a double-edged sword as they may selectively kill cancer cells but may also disrupt the antitumor immune response." (PMID 35111150, 2021). "This indicates that PRMT5 may become a potential biomarker or therapeutic target for cancer." (PMID 34149432, 2021). "Therefore, we identified PRMT5 as a novel activator of NF-κB in cancer." (PMID 33375283, 2020). "PRMT5 might also contribute to hypermethylation of EMT-associated genes, the phenomenon observed in inflamed colonic mucosa in UC and speculated to contribute to the progression from ulcerative lesions to cancer." (PMID 32121248, 2020). "To further confirm that PTEN, p18, p21, p57 and p63, which have been linked with cancer cell growth 38-42, are downstream targets of PRMT5, we designed shRNAs against PTEN, p18, p21, p57 and p63, and knocked down expression of these genes in PRMT5-depleted BGC823 cells." (PMID 32292506, 2020). "Given the fact that PRMT5, YBX1 and NF-κB are all among top crucial factors in cancer progression, pharmacological disruption of this pivotal axis could serve as the basis for new therapeutics for CRC and other PRMT5/YBX1/NF-κB-associated cancers." (PMID 32985589, 2020). "In addition, 53BP1 is correlated to cancer cell survival after DNA damaging treatment, the stabilization of 53BP1 by PRMT5 might contribute to radiotherapy resistance of cancer cells." (PMID 32759981, 2020). "In addition, PRMT5 expression has correlated with MYC or MYCN protein in these cancers." (PMID 31694585, 2019). "Furthermore, these results suggest that inhibition of PRMT5 or methylosome complex formation may potentiate the inhibitory effect of cyclopamine against cancer cells." (PMID 30675521, 2019). "The cleavage of pro-caspases and PARP-1 in the PRMT5 knockdown A549-CFLARL cells was weaker than that in the control knockdown cells after treatment with doxorubicin, suggesting that CFLARL could prevent cancer cells from PRMT5-knockdown-enhanced apoptosis after doxorubicin treatment." (PMID 30736843, 2019).
cancer (continued). "Consequently, PRMT5 inhibitors could potentially eradicate cancer stem cells thereby preventing tumour relapse." (PMID 29876520, 2018). "However, the mechanism by which PRMT5 regulates cancer cell proliferation remains undetermined." (PMID 29441724, 2018). "Indeed, our data showing that treatment of patient-derived BCSCs with the tool PRMT5 inhibitor GSK591 decreases BCSC frequency and proliferation represent, to our knowledge, the first account of a PRMT5 inhibitor influencing cancer stem cells derived from solid cancers." (PMID 29262329, 2017). "Hence, drug targeting PRMT5 in the breast could have a dual effect of not only targeting more differentiated cancer cells but also effectively eliminating the tumor-initiating/BCSC population." (PMID 29262329, 2017). "Thus, we further questioned whether PRMT5 as a novel cofactor of SHARPIN also plays an important role in the invasion of cancer cells." (PMID 28903384, 2017). "Interestingly, although PRMT5-dependent H3K4me3 is a common mechanism for gene regulation in both leukemic and BCSCs, the genes that are targeted appear to be specific to the origin of the cancer stem cell, implying that the cellular mechanisms by which stemness is maintained by PRMT5 are distinct." (PMID 29262329, 2017). "Furthermore, increased expression of PRMT5 in cancer cells led to enhanced cancer-promoting characteristics, including cell proliferation, anchorage-independent growth, and cell migration, clearly highlighting the role of PRMT5 as a tumor promoter in PDAC and CRC." (PMID 28591716, 2017). "However, the role of PRMT5 in cancer development remains to be fully elucidated." (PMID 26078354, 2015). "Interestingly, PRMT5 gene silencing sensitized various cancer cells to TRAIL." (PMID 20977779, 2010). "Indeed, PRMT5 is highly expressed in some cancer cell lines and when knocked down, interferes with cell growth, indicating that it may play a crucial role in silencing tumor suppressors." (PMID 20049127, 2009). "TNG462 is a next‐generation second‐generation inhibitor that targets the PRMT5–MTA complex and is primarily intended for MTAP‐deleted cancers." (PMID 41537447, 2026). "The elevated PRMT5 expression observed in both SCC and ADC tissues is consistent with previous reports demonstrating PRMT5 overexpression in various cancer types." (PMID 41301499, 2025). "Protein Arginine Methyltransferase 5 (PRMT5), an epigenetic regulator involved in diverse cellular processes, is currently under investigation as a therapeutic target in multiple cancer types." (PMID 40864819, 2025). "Protein arginine methyltransferase 5 (PRMT5) is a key regulator of gene expression and RNA splicing, with therapeutic potential demonstrated in MTAP-deleted cancers." (PMID 40846633, 2025). "Another PRMT5 inhibitor of MRTX1719 exhibits synthetic lethality in preclinical models and activity in phase I trial for patients with MTAP-null cancer, The efficacy remains to be investigated in late-stage trials." (PMID 40590219, 2025). "PRMT5 overexpression can result in the activation of NF-kB, AKT, PI3K, and the mTOR/elF4E, contributing to cancer." (PMID 40869229, 2025). "MTA-dependent compounds inhibit PRMT5 activity in an MTA-cooperative manner and selectively kill MTAP-deleted cancer cells while sparing MTAP wild-type (WT) cells." (PMID 40377999, 2025). "Either way, the effectiveness of PRMT5 and MAT2A inhibitors depends on the accumulation of MTA in cancer cells with MTAP gene deletion." (PMID 41465382, 2025). "A range of cancers display aberrant protein‐arginine methylation via type I PRMTs (primarily PRMT1 and PRMT4) and type II PRMTs (principally PRMT5)." (PMID 39964832, 2025).
cancer (continued). "In summary, a rationallydesigned mechanism switch was achievedin a series of compounds that selectively inhibit the PRMT5•MTAcomplex relative to the PRMT5•SAM complex and selectively kill MTAP-deleted cancer cells relative to MTAP WT cells." (PMID 39919252, 2025). "PRMT5 inhibitors have demonstrated synthetic lethality in cancers with MTAP deletions, selectively inducing cancer cell death." (PMID 40846633, 2025). "On the other hand, MRTX1719 selectively targets the PRMT5/metabolite methylthioadenosine (MTA) complex, which is elevated in cancers with the deletion of methylthioadenosine phosphorylase (MTAP)." (PMID 40723820, 2025). "AM-9934 inhibits PRMT5 only in the presence of MTA and selectively impairs proliferation of MTAP -deleted cancer cells and growth of MTAP−/− tumors while sparing MTAP+/+ cells." (PMID 40377999, 2025). "In addition, PRMT5 plays a crucial role in maintaining stem cell identity and suppressing apoptotic pathways in proliferative cells, though the relative contributions of its histone modification and splicing functions in cancer remain unclear." (PMID 40846633, 2025). "MTA acts at the intracellular level by inhibiting the MAT2A/PRMT5/RIOK1 axis, thereby weaponizing this pathway for PRMT5 vulnerability in cancer cells, and synergizing with pemetrexed." (PMID 41583489, 2025). "In cancer cells, an increase in MAT2A expression is observed, which weakens the inhibitory effect of MTA on PRMT5 and slightly increases the histone methylation process in cells with MTAP deletion." (PMID 41465382, 2025). "PRMT5 is also a major regulator of genome stability and HR-mediated DSB repair, with depletion or inhibition sensitising cancer cells to chemotherapeutic DNA-damaging agents including cisplatin and radiotherapy." (PMID 39695328, 2025). "Clinical investigations of the PRMT5-specific inhibitor GSK3326595 are currently being conducted, and the results are promising for preventing cancers." (PMID 39781264, 2025). "This MTAP deletion-induced vulnerability is extend to the MAT2A, the upstream enzymes of PRMT5, and three kinds of MAT2A inhibitor (AG-270, S-095033, and IDE-397) are currently in the phase I clinical trials for the therapy of MTAP-deleted cancers." (PMID 41445748, 2025). "Based on the effect that PRMT5 had on FXR1 levels, we wanted to see if inhibiting PRMT5 demethylated FXR1 and regulated its actions in cancer cells." (PMID 38709899, 2024). "Various phase I/II studies are testing new therapies for the most promising targets, including CAR T and cancer vaccines versus MSLN, PRMT5-MTA, PI3K, andYAP/TEAD inhibitors and PARPi." (PMID 38893092, 2024). "However, the results obtained in this study suggest that PRMT5 can also promote apoptosis via methylation of caspase-8, which may also be important for breaking the resistance of cancer cells and must be taken into account in the design of therapies targeting the methylation networks of the cell." (PMID 38730267, 2024). "Our data demonstrate a role for PRMT5-mediated SDMA in the context of RS-induced transcriptional induction, affecting physiological homeostasis and cancer therapy." (PMID 38838142, 2024). "Highly phosphorylated PRMT5 was tightly complexed with MEP50 in the cytoplasm, followed by the enhancement of HSP90 arginine methylation in NDRG2low ATL and other cancer cells." (PMID 38474089, 2024). "Furthermore, it has been reported that PRMT5 and MEP50 expression is upregulated in various cancers, and the cytoplasmic localisation of PRMT5/MEP50 is associated with a wide variety of cellular processes, including signal transduction pathways that are highly relevant to the pathogenesis of cancer." (PMID 38474089, 2024). "Thus, PRMT5 may maintain STAT3 activation in a variety of cancer types." (PMID 38760429, 2024).